IGF2 (insulin like growth factor 2)
Diseases named in the same sentence as IGF2 in open-access papers (continued):
Sharing a sentence is not in itself a finding about the gene and the disease.
tumor (continued). "Our analysis of this model clearly showed that IGF2 overexpression in the context of constitutive WNT/β-catenin pathway activation only had a moderate effect on tumor progression." (PMID 27471492, 2016). "More importantly, the in vivo functional study showed that miR-663b inhibited tumor growth and repressed IGF2 expression." (PMID 27895308, 2016). "Reestablishment of miR-100 expression levels led to tumor growth inhibition by strongly reducing IGF2 (insulin-like growth factor 2) expression, a known oncogene." (PMID 27187371, 2016). "It is the only medical treatment that can suppress tumor production of IGF2, leading to normal levels of C-peptide, insulin and glucose." (PMID 27134683, 2016). "Rarely, a paraneoplastic syndrome of hypoglycemia occurs due to tumor production of insulin growth factor 2 (IGF2), which is more common in the tumors of the retroperitoneum and liver." (PMID 27672467, 2016). "This biallelic expression pattern is associated with upregulation of IGF2 mRNA and IGF-II protein, leading to tumor growth and CSC self-renewal." (PMID 27275535, 2016). "Future studies are needed to examine if IGF2 is also aberrantly imprinted in CSCs isolated from clinical tumor samples." (PMID 27275535, 2016). "Our meta-analysis was unable to find any statistical significance between HCC tumor tissues and adjacent tissues for the methylation of the remaining two genes, including IGF2 and hMLH1." (PMID 27835605, 2016). "In conclusion, our studies demonstrated that miR-663b is epigenetically regulated by HOTAIR and exerts its tumor-suppressive function via targeting IGF2." (PMID 27895308, 2016). "The additional role of CACNA1G and IGF2 warrants further studies, both to investigate tumor-regulating mechanisms and to confirm the clinical role in larger patient samples." (PMID 25879218, 2015). "In Mitalipov's study, he suggested that hypermethylation within the IGF2/H19 IC in all analyzed primate ESC lines resulted in a risk of cellular overproliferation and tumor formation." (PMID 25879223, 2015). "High expression levels of IGF2 are predictive of aggressive tumor growth and poor prognosis in HCC patients." (PMID 26020769, 2015). "Although additional validation studies using corroborated clinical samples from IGF-1R-targeted therapies must be performed, our current study reveals malignant progression of tumours in the face of an IGF-1R blockade through IGF-2 secretion in the TME." (PMID 26465273, 2015). "Combining an anti-IGF1R antibody with MEDI-573 offers a better antitumor effect because of greater inhibition of IGF1 and IGF2 signaling in cancer cells and tumor angiogenesis is inhibited." (PMID 25699021, 2015). "Another comprehensive study in murine KO models isolated the H19 deletion effect from the effect of Igf2 overexpression, which commonly accompanies H19 deletion, and showed in several tumor models that H19 has tumor suppressing properties." (PMID 26536864, 2015). "It contributes to IGF2 activation in trans and promotes tumor metastasis and predicts poor prognosis in colorectal cancer." (PMID 25884481, 2015). "Cixutumumab-treated tumours of STAT3 shRNA-transfected MDA231–Luc cells showed significant decreases in levels of IGF-2 expression, F4/80+ macrophages (left) and CD34+ VE cells (right) when compared with control tumours." (PMID 26465273, 2015). "IGF2BP1 has been shown to be involved in tumor development by targeting mRNAs such as IGF2 and c-myc." (PMID 25889892, 2015). "It is likely that in these contexts, miR-615-5p is acting as a tumour suppressor through interfering with the insulin-like growth factor 2 (IGF2) transcript." (PMID 26451238, 2015). "Previous studies have suggested that tumour-derived IGF-2 contributes to vasculogenesis by augmenting the recruitment of endothelial progenitor cells through its interaction with IGF-2R57." (PMID 26465273, 2015).
tumor (continued). "In our OS patient’s tumour tissue, the mRNA expression of both IGF2 and H19 has increased significantly (FDR = 3.46E-15 and FDR = 0.0015, respectively)." (PMID 25496518, 2014). "IMP3 has been shown to promote tumor cell proliferation through the upregulation of IGF2, a potent mitogenic factor previously shown to exert effects in a number of diseases." (PMID 25295085, 2014). "This cohort was divided into two groups on the basis of IGF2 mRNA abundance: the tumor was considered as IGF2-high when its expression was at least 25 higher than normal adrenals." (PMID 25089899, 2014). "Basic research studies have demonstrated the tumor-suppressor function for miR-100, regulating several oncogenes, such as insulin-like growth factor 2 (IGF2) and mechanistic target of rapamycin (mTOR)." (PMID 25309903, 2014). "In our analysis of the TCGA data, we indeed found that high IGF2 mRNA expression in tumor tissue significantly correlated with a shortened interval to progression/recurrence, i.e. progression-free survival." (PMID 24932685, 2014). "Intense immunoreactivity was observed for IGF-2 in all paired samples of tumor and background liver." (PMID 25052889, 2014). "In IGF2-low tumors, other growth factors (FGF9, PDGFA) are more expressed than in IGF2-high tumors, suggesting that they play a compensatory role in tumor progression." (PMID 25089899, 2014). "The proliferation rate in tissue culture and the tumor growth kinetics in vivo were similar for stable IGF2 knockdown or control knockdown." (PMID 24932685, 2014). "Genetic and epigenetic mechanisms that determine isolated transcription of mRNA and the production of IGF-2 and big IGF-2 are not well understood; however, these mechanisms are thought to play an important role in carcinogenesis and tumor growth." (PMID 24934576, 2014). "Insulin-like growth factor-2 demonstrated strong immunoreactivity in all patient samples of tumor and adjacent liver, indicating the importance of IGF-2 in early and late stages hepatocarcinogenesis." (PMID 25052889, 2014). "Surprisingly, a preclinical study showed that C/EBPα expression is also upregulated by IGF2; this finding is unexpected considering that the mitogen IGF2 should decrease the expression of tumour suppressor genes such as C/EBPα." (PMID 25225571, 2014). "Insulin-like growth factor 2 gene (IGF2) is a paternally expressed imprinted gene, but IGF2 imprinting is lost in a host of human neoplasm, leading to increased IGF2 expression." (PMID 23900345, 2013). "In this tumor model, somatic inactivation of the Wt1 gene occurs in the context of bi-allelic over-expression of the Igf2 gene in a small subset of differentiating metanephric mesenchymal cells." (PMID 22875335, 2013). "To validate the association between networkinsertions and Igf2 expression, we quantified Igf2 expressionin all of our SB-induced MB tumours for which RNA was available using Real TimePCR." (PMID 24252690, 2013). "This is an important therapeutic criterion as all human cancers are exposed to IGF-1 and IGF-2 due to hepatic endocrine synthesis, tumor stroma expression, and autocrine activation." (PMID 23383308, 2013). "The present study constructed an adenoviral vector for tumor cell targeted therapy based on the principle of LOI of IGF2 in tumor cells." (PMID 23900345, 2013). "IGF2 is a paternally expressed imprinted gene, but IGF2 imprinting is lost in a host of human neoplasm, resulting in biallelic IGF2 expression and abnormally high IGF2 production." (PMID 23900345, 2013). "Although there was still heterogeneity in tumour presentation in both ΔCat and ΔCat;AdIgf2 adrenals at this stage, histo-pathological analysis showed an almost systematic acceleration of tumour progression in the adrenals that overexpressed Igf2." (PMID 22952916, 2012).
tumor (continued). "In tumor-adjacent group, the IGF-2 level was strongly correlated with both ERα (r = 0.8502) and ERβ (r = 0.9327) expressions." (PMID 22720981, 2012). "One surprising finding of our study is the relatively modest effect of Igf2 overexpression on tumour progression in compound transgenics." (PMID 22952916, 2012). "This agrees with the fact that IGF-2R functions as a tumor suppressor to sequester IGF-2 from circulation." (PMID 22720981, 2012). "Altogether, these observations suggested that Igf2 overexpression had a moderate but significant promoting effect on tumour progression in 14 month-old ΔCat mice." (PMID 22952916, 2012). "In our previous study, a recombinant replication-defective adenovirus carrying the IGF2 imprinting system and the DT-A gene was successfully constructed, in which Ad-DT-A effectively kills tumor cells showing IGF2 LOI." (PMID 23171475, 2012). "Formation of malignant tumours is nonetheless a rare event, even when Igf2 expression is further increased by ACTH treatment." (PMID 22952916, 2012). "Upregulation of IGF2 is necessary for tumor formation in vivo and for the proliferation of cultured SS cells." (PMID 22550415, 2012). "We also show that Igf2 overexpression in the context of constitutive β-catenin activation only has a mild promoting effect on tumour progression." (PMID 22952916, 2012). "Based on this explanation, it can be concluded that the expression of IGF-2 gene in invasive BC is related to the transfer of tumor." (PMID 22662119, 2012). "We thus decided to mimic this situation by further inducing Igf2 expression in ΔCat;AdIgf2 adrenals, right before the onset of spontaneous aggressive tumour transition." (PMID 22952916, 2012). "IGFBP-7, although has relatively low affinity toward IGF-1 and IGF-2, exerts a similar anti-tumor effect as its high affinity IGFBP counterpart IGFBP-3." (PMID 21729319, 2011). "As such, IGF-2 was found to be upregulated in both primary RMS tumor samples and cell lines, mechanistically the result of loss of imprinting of the maternal or duplication of the active IGF2 allele." (PMID 21253475, 2011). "In order to summarize the results obtained in this study we have build a hypothetical model-diagram of the EGF/IGF-2 regulatory circuit functioning during the transition from transgenic to tumor state." (PMID 21464922, 2011). "For this, we focused our attention, first of all, on genes specifically upregulated in tumor compared to transgenic state, that encode components of the revealed EGF and IGF-2 pathways." (PMID 21464922, 2011). "It is becoming increasingly evident that the Type-1 insulin-like growth factor (IGF-1R) and its ligands (IGF-1, IGF-2) play roles in both tumor cell proliferation and survival, and proliferation of vascular endothelial cells." (PMID 21197468, 2011). "Recently, this antibody has shown potential antitumor activity in human hepatocarcinomas xenografts, a tumor where upregulation of IGF2 expression is a common alteration." (PMID 21437217, 2011). "Subsequent analysis of key nodes upstream of transcription factors predicted for transgenic and tumor promoter sets revealed a switch from EGF signaling in the pre-tumor state to IGF-2 in the tumor state." (PMID 21464922, 2011). "This marker of an early neuronal phenotype was markedly decreased in hypoxic tumor regions, parallel to induced HIF2α and IGF2." (PMID 20862257, 2010). "The P3 and P4 promoters are the major IGF2 promoters during embryogenesis and tumor development, while P1 is exclusively active in adult liver tissue and P2 activity is rarely detected in adult human tissue." (PMID 21162716, 2010). "By selective killing of cancer cells, which express H19 and IGF2, the treated tumor cells as well as the neighboring tumor cells (as IGF2 mediate its effect in autocrine/paracrine manner) are at least partly deprived of their IGF2 supply." (PMID 21162716, 2010).
tumor (continued). "The expression of IGF2BP3 was significantly and positively correlated with that of IGF-2 in tumor cells (P = 0.02)." (PMID 20178612, 2010). "Of the 40 informative IGF2 tumour samples, 30 tumours were located at the antrum and 10 tumours were located at the gastric corpus." (PMID 19737423, 2009). "Gastric corpus cancer (8/10, 80%) were more likely to have LOI of IGF2 in tumours than antrum cancers (10/30, 33.3%){odds ratio (OR) = 8, 95% confidence intervals (CI) = 1.425-44.920, p = 0.018)}." (PMID 19737423, 2009). "Quantitative real-time reverse transcription-PCR analysis showed that although 15 of 20 tumours had a higher level of IGF2 mRNA than normal liver tissues, 15 of 20 tumours had a lower level of H19 mRNA than normal liver tissues." (PMID 19034281, 2008). "H19 mRNA levels were higher in 13 HB tumours with ROI than in 7 HB tumours with IGF2 alterations (P<0.01 by Welch's t-test)." (PMID 19034281, 2008). "The P3 promoter was unmethylated in 5 of 7 tumours with IGF2 alterations; UPD, 11p15 loss or LOI, but in 4 of 13 tumours with ROI." (PMID 19034281, 2008). "In contrast, 7 tumours with IGF2 alterations expressed very low levels of H19 mRNA, whereas 11 of 13 tumours with ROI expressed a substantial amount of H19 mRNA; 2 tumours (nos." (PMID 19034281, 2008). "(iv) Insulin-like growth factor 2 mRNA binding protein 3 (IGF2BP3), is found in the nucleolus, is over-expressed in human tumours and represses IGF2 during late development." (PMID 18416826, 2008). "The present and earlier studies showed that all HB tumours with UPD and the majority of HB tumours with LOI or ROI expressed the higher levels of IGF2 mRNA than normal liver tissues." (PMID 19034281, 2008). "Of 21 tumours whose RNA was available, 9 and 12 tumours had heterozygous and homozygous ApaI/AvaII sites in exon 9 of IGF2, respectively." (PMID 19034281, 2008). "Of the nine heterozygous tumours, seven showed monoallelic expression of IGF2, indicating ROI, and two showed biallelic expression of IGF2, indicating LOI, and the results were consistent with those examined by COBRA and SNP array analyses." (PMID 19034281, 2008). "Quantitative RT–PCR analysis showed minimal expression of H19 mRNA and substantial expression of IGF2 mRNA in tumours with LOH or LOI, and substantial expression of both H19 and IGF2 mRNAs in tumours with ROI." (PMID 19034281, 2008). "In HB, although LOH of IGF2 was reported in 20–30%, the incidence of LOI of IGF2 was uncertain because each series included only a small number of HB tumours." (PMID 19034281, 2008). "All 3 tumours with UPD, 1 of 1 with 11p15 loss, 1 of 3 with LOI and 10 of 13 with ROI, expressed higher levels of IGF2 mRNA than normal liver tissues." (PMID 19034281, 2008). "It is intriguing that three tumours (#23–25) showed alterations of both IGF2/H19 and KIP2/LIT1 imprinted domains, because each domain is independently regulated, and BWS with both alterations is very rare." (PMID 16909133, 2006). "A total of 25 (71%) tumours showed alteration of IGF2/H19 or KIP2/LIT1 or both of the domains, of which 10 showed LOH, 11 showed IGF2 LOI only, one showed DMR-LIT1 hypomethylation only, and three showed both IGF2 LOI and DMR-LIT1 hypomethylation." (PMID 16909133, 2006). "The M6P/IGF2 receptor is involved in the transport of lysosomal enzymes and is considered a tumour suppressor gene by virtue of its capacity to bind, internalise, and degrade peptide growth factors including IGF-2." (PMID 12618883, 2003). "We identified potential oncogenes, including Igf2, Hras, Fgf3, Fgf4, and Ccnd1 in this amplicon that could promote tumor growth in mBT0309." (PMID 41568176, 2026). "Nonetheless, it is apparent from this study that IGF2 promotes tumor growth in mBT0309, which could be, in part, due to macrophage polarization." (PMID 41568176, 2026).
tumor (continued). "Expression of Igf1r and Insr in diverse TME cell types suggests that IGF2 could have paracrine signaling effects that create an immunosuppressive tumor-promoting niche." (PMID 41568176, 2026). "Our analyses of mBT0309 and human datasets suggest that IGF2 may influence tumor growth by signaling to multiple cell types, including myeloid cells and vascular cells." (PMID 41568176, 2026). "More importantly, IGF2 secreted by Scissor+ tumor cells could act on themselves through IGF2-IGF1R/IGF2R interactions." (PMID 40098972, 2025). "The insulin-like growth factor II (IGF2) system represents a crucial pathway in the tumor biology of ACC: even though the access to IGF2 immunohistochemistry is not widely available, his expression has been shown to be the best diagnostic ancillary tool in ACCs." (PMID 40214939, 2025). "This suggests that fusion-positive cells might maintain a pseudo-hypoxic state via autocrine IGF2-Akt signaling, a mechanism described in other tumor types and referred to as “growth factor-driven HIF activation”." (PMID 41174561, 2025). "In this respect, HIF-1α may induce the increased expression of VEGF, glycolytic enzymes, IGF2, and Bcl-2 genes, which facilitate the tumor cells’ adaptation to the hypoxic tumor microenvironment, by stem cells’ survival." (PMID 40227577, 2025). "Increased levels of p‐AKT in starved CAFs were induced by treatment with tumor cell‐conditioned medium (TC‐CM) from KD‐circSMEK1 HCC cells—which contains elevated IGF2 due to enhanced secretion—or by direct stimulation with exogenous recombinant IGF2." (PMID 41103217, 2025). "Radiotherapy, as a non-invasive means, may inhibit tumor IGF-2 secretion by local irradiation and could be an innovative therapeutic option for inoperable DPS." (PMID 41367853, 2025). "This co-localisation may indicate a synergistic effect, potentially enhancing the IGF2 dependent signalling pathways that contribute to aggressive tumour behaviour." (PMID 40038716, 2025). "On the one hand, Scissor+ tumor cells secreted ligands that activated IGF2 and PDGF signaling pathways which could regulate the transformation of fibroblasts into CAFs." (PMID 40098972, 2025). "Finally, we demonstrated that CEBPβ up-regulated IGF2 expression in tumor senescent ECs by combining with Igf2-promtor-sequence." (PMID 39674501, 2025). "Therefore, the collective data suggest CD34+CLDN5+ ECs promoted the development of CCA and recruited MSCs into TME, with these ECs exhibiting elevated expression of IGF2 within the tumor." (PMID 39674501, 2025). "Igf2-cKO mice treated with anti–PD-1 demonstrated the most effective tumor retardation, significantly prolonged survival, and exhibited increased infiltration of T cells, along with enhanced antitumor activity of CD8+ T cells compared with WT mice treated with anti–PD-1." (PMID 39545420, 2024). "In addition, injection of CAFs at the eradicated tumor site accelerate tumor recurrence, which is eliminated by IGF2 knockdown or 3-MA treatment." (PMID 38467935, 2024). "In vivo models reveal that stromal cells, not tumor cells, are major sources of IGFs, with non-immune stromal cells and tumor-associated macrophages (TAMs) expressing Igf1 and Igf2 mRNA." (PMID 39273251, 2024). "It is worth to note that this study only indicated that the manipulated tumor cells may secrete IGF2 to activate CAFs; however, whether IGF2 secreted by primary cancer cells can activate fibroblast has not been evaluated." (PMID 39759028, 2024). "Notably, C2 IGF2+ tumor cells demonstrated the ability to engage in paracrine interactions with fibroblasts, resulting in a substantial communication intensity between these cell populations." (PMID 39896800, 2024). "Considering the widespread expression of PD-L1 in the TME, this indicates that IGF2 released by CAFs may also upregulate the expression of PD-L1 on other cells, such as tumor cells, in addition to CAFs." (PMID 39545420, 2024).